ZGPAT (zinc finger CCCH-type and G-patch domain containing)
Description:
Transcription repressor that specifically binds the 5'-GGAG[GA]A[GA]A-3' consensus sequence. Represses transcription by recruiting the chromatin multiprotein complex NuRD to target promoters. Negatively regulates expression of EGFR, a gene involved in cell proliferation, survival and migration. Its ability to repress genes of the EGFR pathway suggest it may act as a tumor suppressor. Able to suppress breast carcinogenesis. [Isoform 4]: Antagonizes the transcription repression by isoform 1 by competing for the binding of the NuRD complex. Does not bind DNA.
Synonyms: GPATC6; GPATCH6; KIAA1847; ZC3H9; ZC3HDC9; ZIP; dJ583P15.3; MGC44880; FLJ14972
Tractability: Antibody: its Gene Ontology location is reachable by antibodies, with high confidence. PROTAC: UniProt records ubiquitination sites on it; ubiquitination databases record sites on it; its protein half-life has been measured.
Gene: Protein-coding gene on chromosome 20 (63,707,353 to 63,736,150, forward strand). Ensembl gene ENSG00000197114.
Subcellular location: Nucleus; Nucleus (Isoform 4)
Subcellular location (Human Protein Atlas): Nucleoplasm; Plasma membrane
Gene Ontology:
Molecular function: DNA-binding transcription factor activity; DNA-binding transcription repressor activity, RNA polymerase II-specific; protein binding; RNA polymerase II cis-regulatory region sequence-specific DNA binding; sequence-specific DNA binding; DNA-binding transcription factor activity, RNA polymerase II-specific; metal ion binding; nucleic acid binding
Biological process: negative regulation of DNA-templated transcription; negative regulation of epidermal growth factor-activated receptor activity; negative regulation of transcription by RNA polymerase II
Cellular component: nucleoplasm; nucleus; chromatin
Genetic constraint (gnomAD): Loss-of-function variants: 39 observed, 46.26 expected, observed/expected ratio (o/e) 0.84, 90% interval 0.65 to 1.1. The upper end of that interval is the gene's LOEUF score, 1.1, which puts it in group 4 of 6, group 1 being the genes least tolerant of losing a copy. Missense variants: 717 observed, 673.26 expected, observed/expected ratio (o/e) 1.07, 90% interval 1 to 1.13. Synonymous variants: 348 observed, 290.18 expected, observed/expected ratio (o/e) 1.2, 90% interval 1.1 to 1.31.
Homologues: Orthologues: chimpanzee ZGPAT (99% identical), macaque ZGPAT (97% identical), guinea pig ZGPAT (80% identical), mouse Zgpat (80% identical), pig ZGPAT (79% identical), rat Zgpat (79% identical), dog ZGPAT (77% identical), tropical clawed frog zgpat (57% identical), zebrafish zgpat (51% identical), Drosophila melanogaster CG4709 (30% identical), Caenorhabditis elegans zgpa-1 (22% identical). Paralogues in human: TFIP11 (16% identical), LIME1 (8% identical).
Diseases named in the same sentence as ZGPAT in open-access papers:
ZGPAT is named in the same sentence as 3 diseases in open-access papers, as found by Europe PMC text mining. Sharing a sentence is not in itself a finding about the gene and the disease. The quoted sentences say what the papers report.
infection (1 paper, 2021). The state of being infected such as from the introduction of a foreign agent such as serum, vaccine, antigenic substance or organism. "ZGPAT and CHD5 were found only in leukocytes with H37Rv strain infection." (PMID 34141493, 2021).
tumor (1 paper, 2020). "These sites were annotated to genes involved in diverse biological pathways, including neurological development (AHNAK, PGAP3), lymphocytic function (ITGAL), apoptosis (RELT), tumor suppression (ZGPAT), and endothelial-to-mesenchymal transition (PRSS23)." (PMID 32084330, 2020).
ZGPAT also shares sentences with these, for which no sentence is quoted: Intellectual disability (1 paper).